RAB27A (RAB27A, member RAS oncogene family)
Diseases named in the same sentence as RAB27A in open-access papers (continued):
Sharing a sentence is not in itself a finding about the gene and the disease.
tumor (continued). "However, in MC38 tumor models, PD-L1 knockout plays a more critical role than Rab27a loss does." (PMID 31647023, 2019). "In addition, knockdown of Rab27A and Rab27B is associated with increased accumulation of tumor-suppressive miRNA within bladder cancer cells, suggesting the secretion of tumor-suppresive miRNA through exosomes may be critical for tumor progression." (PMID 30925917, 2019). "The knockout of Rab27A in colorectal cancer models significantly reduced exosome secretion and suppressed tumor growth." (PMID 40728994, 2025). "Rab27A suppression has been shown to reduce tumor growth and metastasis in melanoma and breast cancer models, possibly due to a decrease in bone marrow recruitment." (PMID 40722712, 2025). "This study investigated novel therapeutic targets to treat DOXIC through the knockdown of Rab27a in tumor tissues to block the release of EXOs." (PMID 40360476, 2025). "Nevertheless, analysis of secondary organs determined augmented MCF7.Gluc metastasis in liver and bones and tumour self‐seeding in mice co‐implanted with Rab27a WT CAFs." (PMID 40091448, 2025). "In rescue experiments, Rab27a knockdown reduced EV secretion from the tumor, and KC inactivation led to decreased lipid deposition in the liver." (PMID 40612230, 2025). "Further, this technique was utilized in an immunocompromised mouse model of PDAC, where Rab27a KD decreased tumor growth." (PMID 41137505, 2025). "We, therefore, used CRISPR to reduce protein expression of Rab27a or Rab27b in both micrometastatic and primary tumor cells and measured EV release into their conditioned media." (PMID 40488669, 2025). "Overexpression of Rab27a increases exosome secretion and elicits efficient antitumor immunity, thus suppressing tumor formation in a tumor mouse model." (PMID 38695990, 2024). "Further analysis showed that HSPA5 was significantly expressed in tumor tissues and co-expressed with Rab27A protein." (PMID 38521810, 2024). "HIF‐1α promotes the creation of CD19+ extracellular vesicles (EVs) in tumour B cells by increasing Rab27A expression." (PMID 38997802, 2024). "Considering that the RAB27A OE cell exosome media contained more tumor suppressor miRNAs, the cellular uptake of these exosomes probably inhibited cancer cell metastasis." (PMID 38685086, 2024). "The resected xenograft tumor tissues were analyzed using IHC and qRT-PCR to verify the expression of Rab27A." (PMID 38521810, 2024). "The oncogenic function of Rab27a is mainly due to its function as regulator of exosome secretion, which modulates cancer cell function and tumor microenvironment." (PMID 39008536, 2024). "(e) Analysis of PBMC infiltration and tumor cell survival in HepG2 spheroids co-expressing shRNA targeting mutated ß-catenin (shßcat MUT) and control siRNA (siCtrl) or siRNA targeting Rab27A (siRab27A)." (PMID 39008536, 2024). "Studies have shown that Rab27a can effectively inhibit the secretion of exosomes from tumour cells, thereby interfering with tumour progression." (PMID 38302430, 2024). "Rab27A and Rab27B contribute to tumor formation progression in many types of cancer through various mechanisms, including the secretion of small extracellular vesicles (sEVs)." (PMID 39596498, 2024). "Taken together, the in vivo metastasis assays showed that cerdulatinib can reverse the tumor proliferation mediated by overexpression of RAB27A and plays an antitumor role in vivo." (PMID 38521810, 2024). "Inhibiting exosome secretion with GW4869 and exosome uptake using 5-(N-ethyl-N-isopropyl)-amiloride suppressed tumor growth in an ES-2 xenograft mouse model of ovarian cancer, and Rab27a knockdown inhibits tumor growth and increases survival in mice." (PMID 38796525, 2024). "Rab proteins, including Rab27a, are involved in the transport of pathogens and tumor cell development, maturation, and migration." (PMID 38715944, 2024).
tumor (continued). "Progressive loss of gene expression from healthy pancreas to undifferentiated cancer tissue suggests a tumor suppressive role for Rab27a." (PMID 37641131, 2023). "Our xenograft model revealed that in vivo, cSCC tumor growth was significantly impaired by RAB27A-depletion, suggesting that cancer cell-derived EVs are critical for tumor growth." (PMID 37495566, 2023). "Taken together, our data reveal that EV-secretion inhibition in cSCC cells resulted from RAB27A-depletion impaired tumor growth in vivo." (PMID 37495566, 2023). "Meanwhile, immunohistochemistry (IHC) staining showed the protein level of HIF1A was highly elevated in both iWAT and eWAT from 4T1/Ctrl mice when compared with 4T1/miR-204 KO, 4T1/Rab27a KO or tumour free mice." (PMID 37620316, 2023). "Strikingly, 4T1/Ctrl mice displayed much shrinking eWAT and iWAT morphology than tumour-free or 4T1/Rab27a KO mice and lower eWAT, iWAT, gastrocnemius (GA) and tibial anterior (TA) weight were detected." (PMID 37620316, 2023). "RAB27A is a member of the small GTPase family and suppresses cell motility and invasion in various human cancers as a tumor suppressor." (PMID 37438760, 2023). "During 5 days of co-culturing, significant HUVEC sprouting toward the tumor spheroids of ASPS cells occurred; however, the sprouting effect was significantly suppressed by Rab27a or Sytl2 knockout and ASPSCR1::TFE3-expression loss." (PMID 37029109, 2023). "Considering the potential roles of RAB27A in tumor migration, we subsequently invested the expression level of RAB27A in the metastatic tumor sites within lymph nodes and observed a significant elevation in RAB27A expression compared to the primary sites." (PMID 37685910, 2023). "Meanwhile, immunohistochemical staining results revealed that Rab27a expression was downregulated in the tumor tissues of the sh-Rab27a- or Nexinhib20-treated mice." (PMID 37005676, 2023). "Both the 4T1/Ctrl mice and 231/Ctrl mice demonstrated hypermetabolism, with obviously elevated oxygen consumption rate than either tumour free mice, 4T1/Rab27a KO or 231/Rab27a KD mice." (PMID 37620316, 2023). "Despite comparable proliferation rates in vitro, significant suppression of in vivo tumor development was observed by Pdgfb, Rab27a, Sytl2, and Vwf knockout." (PMID 37029109, 2023). "The inhibition of RAB27A-mediated secretion of EVs interfered with cSCC tumor growth in vivo suggesting a role for EVs in the tumor-stroma-communication in cSCC." (PMID 37495566, 2023). "Consistent pattern was detected in 4T1/Ctrl versus tumour-free, 4T1/miR-204 KO or 4T1/Rab27a KO mice." (PMID 37620316, 2023). "Tumor growth of miR-124-3p mimic transfecting group was significantly reduced compared to the mimic NC transfecting group, and the re-expression of Rab27a restored tumor growth." (PMID 36600320, 2023). "In contrast, RAB27A mRNA and protein levels were evidenced to be lower in GC tissues than in adjacent tumor tissues, showing a reverse correlation with miR-182 expression." (PMID 37438760, 2023). "In this context, we assessed the clinical value of 8 genes (RAB2B, RAB3B, RAB9A, RAB11B, RAB27A, RAB27B, STX1A, and VAMP7), which are implicated in sEVs biogenesis, as well as their association with overall and tumor-derived plasma sEVs levels." (PMID 36980570, 2023). "Compared with B16-F10 Rab27a-/- tumor-bearing mice, B16-F10 Ldha-/; Rab27a-/- tumor-bearing mice showed a reduction in only the lactate level, not the sEV level." (PMID 36531060, 2022). "Consistently, decreased αPD-L1 was observed in blood monocytes and liver and spleen macrophages of the MC38 Rab27a−/− tumor-bearing mice." (PMID 36220994, 2022). "It has been reported that RAB27A highly expresses in CRC tumor tissues compared with matched adjacent tissues, and high level of RAB27A protein positively correlates with lymph node metastasis and TNM stage but indicates favorable prognosis." (PMID 36371494, 2022).
tumor (continued). "To directly verify that the binding of endogenous TEVs affects the in vivo distribution of αPD-L1, we transferred αPD-L1 into the MC38 Rab27a−/− tumor-bearing mice." (PMID 36220994, 2022). "Several studies have demonstrated that Rab27a blockade decreased primary tumor growth and the number of metastatic lung foci in 4T1 cell-transplanted mice but not in TS/A cell-injected mice." (PMID 35053535, 2022). "It has been reported that Rab27a promotes tumor growth via increasing VEGF and TGF-β secretion in vitro." (PMID 36303180, 2022). "Rab27A and Rab27B have been reported to be the primary components of vesicle trafficking in exosome secretion and play critical roles in tumor progression and metastasis." (PMID 36303180, 2022). "Next, we used the MC38 Rab27a−/− tumor-bearing mice to elucidate the role of TEVs in the PLX3397-mediated enhanced antitumor effect of αPD-L1." (PMID 36220994, 2022). "To evaluate the effect of endogenous TEVs on αPD-L1 antitumor activity, we used Rab27a-deficient MC38 cells (MC38 Rab27a−/−) with impaired TEV secretion to establish tumor-bearing mice." (PMID 36220994, 2022). "WT, nSMase2−/−, Rab27a−/− or CD73−/− GL-261 cells were implanted into the brain of C57BL/6J mice to observe differences in tumour growth." (PMID 34753903, 2021). "By contrast, Rab27a overexpressed cell-derived exosomes has been shown to suppress tumor formation in vivo in a mouse model, which is related to cytokines." (PMID 34141705, 2021). "For instance, Rab27a, which directs exosome secretion by controlling the docking of MVBs to the plasma membrane, promotes breast and melanoma tumor growth and metastasis in mice and predicts poor survival in human pancreatic cancer." (PMID 33404012, 2021). "It has also been shown that Rab27a/b-induced exosome secretion reduces the intracellular level of tumor-suppressive microRNA and thereby increases invasion of metastatic cells." (PMID 34483204, 2021). "To explore how NorCA affects tumor-derived Exos, we measured the protein expression of NSMase and RAB27A, which regulate the synthesis and secretion of Exos." (PMID 34888230, 2021). "With this work, RalA and RalB add to the list of proteins known to control exosome secretion and to affect tumor progression, such as Rab27a, Alix, syntenin, and components of the ESCRT machinery." (PMID 33404012, 2021). "Rab27 has been shown to control the exosome secretion pathway, and knockdown of either Rab27a or Rab27b inhibits this pathway in the tumor cell line HeLa B6H4." (PMID 34483204, 2021). "Co-secretion of Rab27a-dependent exosomes contributes to the mobilization of tumor-promoting neutrophils and supports the growth of mouse breast tumors and their metastasis to the lung." (PMID 34141705, 2021). "Rab27 isoforms are also essential for exosomes secretion: the silencing of Rab27A induces a decrease in EV secretion in tumor cell lines." (PMID 34205256, 2021). "Rab27a knockdown (KD) in tumour cells considerably enriched the performance of anti-PD-1 treatment and inhibited 4 T1 tumour development." (PMID 33081785, 2020). "We observed marked changes in the frequency of myeloid cells with Rab27a knockdown in the primary tumor." (PMID 32355248, 2020). "To understand how expression of Rab27a affects tumor progression in an immune-competent model, we pre-conditioned mice by implanting primary tumors for two weeks." (PMID 32355248, 2020). "Consistent with this idea, downregulation of Rab27a led to decreases in myeloid subsets both at the primary tumor site and distant sites such as spleen, lung, and liver." (PMID 32355248, 2020). "Both tumor weight and tumor volume (Fig. 4DII) were significantly suppressed when Rab27a or TRAF3IP2 was silenced." (PMID 32483202, 2020). "Overall, expression of Rab27a in the primary tumor has distinct consequences for the composition of immune milieu at the primary tumor and distant organ sites with the most significant effects seen in the liver." (PMID 32355248, 2020).
tumor (continued). "Significantly, Rab27a KD in tumour cells considerably improved the performance of anti-PD-1 treatment and inhibited 4 T1 tumour development." (PMID 33081785, 2020). "Genetic knockout of Rab27a or nSMase2, which leads to removal of exosomal PD-L1, inhibits tumor growth, even in models resistant to anti-PD-L1 antibodies." (PMID 33168028, 2020). "Knockdown (KD) of Rab27a (MDAKDRab27a) or TRAF3IP2 (MDAKDTRAF3IP2) in triple negative MDA-MB231 cells reduced tumor growth by 70–97% compared to wild-type tumors (MDAw)." (PMID 32483202, 2020). "Inhibitors related to exosomal genes that mediate exosome release, e.g., Rab27a and Plectin, can suppress exosome secretion, leading to tumor suppression." (PMID 33168028, 2020). "Rab27a KD in metastatic melanoma and malignant breast tumour cells resulted in a significant decline in EV generation, primary tumour sizing, and metastasis." (PMID 33081785, 2020). "In contrast, the growth rate of subcutaneous tumors formed from GL-261nSMase2−/−, Rab27a−/−, or LGALS9−/− cells was much slower, and the survival times associated with these cells were also significantly longer than that of GL-261 WT tumor-bearing mice." (PMID 33093453, 2020). "Blocking of exosomal transfer of miR-494 by a knockdown (KO) of Rab27a induced cellular apoptosis and inhibited tumor growth and metastasis in vitro and in human xenografts." (PMID 32709086, 2020). "Human MDSCs promoted SW480 cell growth, but the knockdown of Rab27a in MDSCs diminished tumor growth." (PMID 31559140, 2019). "While the function of Rab27A and Rab27B in exosome release has been established in a number of models, Rab27A has additional exosome-independent roles in tumor progression." (PMID 30925917, 2019). "Knockdown of Rab27A in hCPCs, previously shown to affect EV secretion in tumor cells, also reduced the number of EVs secreted from hCPCs." (PMID 30456736, 2019). "Using genetic knockouts for Rab27a and nSMase2 and exogenously introduced exosomes, we show that exosomal PD-L1 from tumor cells promote tumor growth in an immune-dependent fashion." (PMID 30951669, 2019). "Mice injected with either Pd-l1 or Rab27a null TRAMP-C2 cells on one flank not only suppresses growth of the local tumor cells but also blocks WT tumor cells rechallenged on the other flank in 90 days." (PMID 31647023, 2019). "The oncogenic function of Rab27A/B is likely due to its function in regulating exosome secretion, which modulates cancer cell function and the tumor microenvironment." (PMID 30081925, 2018). "Rab27A-dependent exosome release has been shown to promote tumor growth and metastasis by increasing the mobilization of neutrophils." (PMID 30081925, 2018). "Rab27A/B-induced exosome secretion reduces the intracellular level of tumor-suppressive microRNAs, including miR-23b and miR-921." (PMID 30081925, 2018). "Recent reports have indicated the involvement of Rab27A and Rab27B in promoting cell invasion and tumor metastasis." (PMID 30081925, 2018). "Immunohistochemical (IHC) analysis of 67 HCC tissues and matched non-tumour tissues indicated that the latter samples showed higher levels of Rab27a than the former ones." (PMID 29725020, 2018). "Although the mechanisms are not fully understood, Rab27A-dependent exosome secretion has been shown to contribute to the mobilization of BMDCs, which leads to increased tumor growth and metastasis." (PMID 30081925, 2018). "In vivo analysis on Rab27A inhibition demonstrates effects on the tumor stroma, opposing the effects of miR-142-3p over-expression." (PMID 28146434, 2017). "Rab27a, a member of the Rab family, can regulate the tumor microenvironment and promote tumor growth." (PMID 29212243, 2017). "Rab27A knockdown tumors showed decreased growth, blood vessel density, and vascular function, and increased tumor hypoxia." (PMID 28146434, 2017).
tumor (continued). "Our research results showed that in NSCLC cell level, interference gene Rab27a decreased significantly the proliferation and invasion of tumor, promoted apoptosis, and increased the sensitivity to chemotherapy drugs of NSCLC." (PMID 29212243, 2017). "Rab27a, a member of the Rab protein family, can regulate the tumor microenvironment and promote the development of the tumor." (PMID 29212243, 2017). "Future studies will demonstrate the mechanism by which Rab27A promotes vascular density, and tumor cell growth." (PMID 28146434, 2017). "In tumor implanting nude mice model, tumor initiation rates and tumor sizes were enhanced by Rab27A with obvious angiogenesis." (PMID 27556511, 2016). "The small GTPases Rab27A regulates autocrine and paracrine cytokines by monitoring exocytosis of extracellular vesicles, and is reported to promote certain tumor progression." (PMID 27556511, 2016). "Rab27A is the key protein for intracellular secretion, and was reported to promote tumor progression." (PMID 27556511, 2016). "Rab27A promotes tumor progression by mediating the secretion of cytokines and exosomes in tumor microenvironment." (PMID 25823663, 2015). "Another study in mammary carcinoma cells led to decreased primary tumor growth and lung dissemination upon a blockade of RAB27a." (PMID 27088079, 2015). "Rab27A modulated the tumor microenvironment and facilitated tumor development by regulating exocytosis of multivesicular endosomes and lead to exosome secretion." (PMID 26070933, 2015). "For instance, the secretion of exosome critically needs the present of Rab27A and the functions of tumor exosomes were dual." (PMID 26070933, 2015). "Rab27A also affected exosome secretion, modified tumor microenvironment and finally promoted tumor progression." (PMID 26070933, 2015). "High Rab27A expression was observed in 64 (57.1 %) of the 112 CRC samples compared with 47 (41.6 %) of 113 matched normal tumor-adjacent tissue samples." (PMID 26070933, 2015). "Total RNA was extracted from 18 CRC tissues as well as matched tumor adjacent tissues, and then subjected to one-step qPCR to detect Rab27A mRNA expression." (PMID 26070933, 2015). "Rab27a knockdown attenuated Du145 exosome secretion and subsequent tumour–stroma interactions, failing to induce stromal differentiation or promote tumour growth in vivo." (PMID 26082317, 2013). "Here, we used the same approach of Rab27a inhibition, in order to inhibit secretion of exosomes by mouse tumor cells." (PMID 24009879, 2012). "Moreover, compared with animals singly implanted with MCF7.Gluc cells, no significant alterations were observed upon co‐implantation with Rab27a KD CAFs or DMA treatment regarding metastasis or tumour self‐seeding." (PMID 40091448, 2025). "The enhanced infiltration of CD8α+ T cells into the tumor microenvironment in Rab27a/b-deficient mice does not mitigate tumor progression or increase animal survival relative to tumor-bearing controls (WT and dHET)." (PMID 40408475, 2025). "Moreover, in 168 NSCLC tissues and paired tumor-adjacent normal tissues, IHC analysis showed that the protein expression level of Rab27A was higher in NSCLC tissues than tumor-adjacent tissues." (PMID 38521810, 2024). "The PNI score indicated that KRASG12D‐related PDAC was associated with increased nerve density and severity of PNI compared to other KRAS subtypes, whereas inhibition of EV secretion in Rab27a‐knock out (KO) mice suppressed the severity of neural infiltration in PANC‐1‐induced tumor tissues." (PMID 39488792, 2024). "A study on prostate cancer exosomes and tumor antigen presentation found that exosomal Rab27a could induce the expression of CD73 on DCs." (PMID 36899389, 2023). "In addition, high tumor expression of RAB27A, RAB27B, RAB9A, RAB11B, and STX1A was favorable of a 5-year survival (p = 0.038, p = 0.015, p = 0.008, p = 0.002, and p = 0.028, respectively)." (PMID 36980570, 2023).